SYCE1L (synaptonemal complex central element protein 1 like)
Description:
May be involved in meiosis.
Synonyms: MRP2
Tractability: No criterion of Open Targets' tractability assessment is met for any kind of drug.
Gene: Protein-coding gene on chromosome 16 (77,199,408 to 77,213,215, forward strand). Ensembl gene ENSG00000205078.
Subcellular location (Human Protein Atlas): Intermediate filaments
Gene Ontology:
Biological process: synaptonemal complex assembly; synaptonemal complex organization
Cellular component: synaptonemal complex
Genetic constraint (gnomAD): Loss-of-function variants: 51 observed, 38.44 expected, observed/expected ratio (o/e) 1.33, 90% interval 1.06 to 1.67. The synonymous counts are far from expectation, so gnomAD's model fits this gene poorly and the ratio says little. Missense variants: 426 observed, 283.26 expected, observed/expected ratio (o/e) 1.5, 90% interval 1.39 to 1.63. Synonymous variants: 147 observed, 106.05 expected, observed/expected ratio (o/e) 1.39, 90% interval 1.21 to 1.59.
Homologues: Orthologues: chimpanzee SYCE1L (98% identical), macaque SYCE1L (94% identical), dog SYCE1L (67% identical), rat Syce1l (57% identical), guinea pig SYCE1L (56% identical), mouse Syce1l (55% identical), tropical clawed frog syce1 (31% identical), zebrafish si:ch211-199g17.9 (23% identical). Paralogues in human: SYCE1 (54% identical).
Diseases named in the same sentence as SYCE1L in open-access papers:
SYCE1L is named in the same sentence as 1 disease in open-access papers, as found by Europe PMC text mining. Sharing a sentence is not in itself a finding about the gene and the disease. The quoted sentences say what the papers report.
Infertility (1 paper, 2025). "The SYCE1 gene encodes synaptonemal complex central element protein 1 (<−1.7-fold) and SYCE1L (<−1.6-fold), which are expressed in the synaptonemal complex of meiotic chromosomes and whose deficiency is linked to infertility in mice, both downregulated in LCFs." (PMID 41205594, 2025).